RNF6 (ring finger protein 6)
Diseases named in the same sentence as RNF6 in open-access papers (continued):
Sharing a sentence is not in itself a finding about the gene and the disease.
gastric cancer (5 papers, 2020 to 2022). A primary or metastatic malignant neoplasm involving the stomach. "Thus, we selected Mdm2 and RNF6 in the present study to explore the molecular mechanism underlying the inhibitory effect of GLA in gastric cancer cells." (PMID 35814430, 2022). "In gastric cancer, RNF6 regulates cancer cell growth by affecting the SHP-1/STAT3 signaling pathway." (PMID 35369571, 2022). "Recent studies have shown that RNF6 expression is upregulated in several cancers including colorectal, breast, prostate and gastric cancers." (PMID 35369571, 2022). "For example, the expression level of RNF6 was upregulated in both tumor samples and cell lines of gastric cancer." (PMID 35223862, 2021). "Knockdown of RNF6 in gastric cancer cell lines resulted in significant inhibition of cell growth and decreased expression of cyclin D1 and the anti-apoptotic protein Mcl-1 and sensitizing cells to the cytotoxic effects of doxorubicin." (PMID 35822825, 2020). "As in gastric cancer cells, in this case, downregulating the RNF6 stabilized SHP1, inhibiting the STAT3 pathway, which resulted in cancer cell growth inhibition." (PMID 35822825, 2020). "Mdm2 and RNF6 are classified as oncogenes in various types of cancer, including gastric cancer." (PMID 35814430, 2022). "A recent study confirmed that RNF6 is an oncogene for gastric cancer." (PMID 34081837, 2021). "That study proposed a promising role of RNF6‐SHP‐1‐STAT3 in gastric cancer cell growth." (PMID 34081837, 2021). "The inhibitory effect of GLA on gastric cancer and the expression of MDM2 and RNF6 was also validated in in vivo study." (PMID 35814430, 2022). "Our previous screening of the genes that are regulated by GLA in gastric cancer cells revealed that Mdm2 and RNF6 were the most downregulated genes, among others, in response to GLA treatment in gastric cancer cells." (PMID 35814430, 2022). "Furthermore, knockdown of RNF6 significantly increased the cleavage of PARP and promoted cell apoptosis through the SHP-1/STAT3 signaling pathway, which eventually inhibits gastric cancer cell growth." (PMID 35223862, 2021).
esophageal squamous cell carcinoma (4 papers, 2017 to 2023). Esophageal squamous cell carcinoma (ESCC) is a type of esophageal carcinoma (EC) that can affect any part of the esophagus, but is usually located in the upper or middle third. "Conversely, RNF6 was first found to be mutated on chromosome 13q12 and acted as a tumor suppressor in human esophageal squamous cell carcinoma." (PMID 34081837, 2021). "Mutated RNF6, which is located on chromosome 13q12, was first found to regulate human esophageal squamous cell carcinoma as a tumor suppressor." (PMID 34081837, 2021). "Initially, the RNF6 gene was considered a tumor suppressor gene because of somatic mutations in esophageal squamous cell carcinoma (ESCC)." (PMID 35822825, 2020). "Because of its mapping to chromosome 13q12 and mutations in human esophageal squamous cell cancers, RNF6 was originally believed as a tumor suppressor gene." (PMID 28223545, 2017). "This study aimed to investigate RING-Finger Protein 6 (RNF6) expression in esophageal squamous cell carcinoma (ESCC) cells and whether it affects cell proliferation, invasion, and migration by regulating the TGF-β1/c-Myb pathway." (PMID 36845743, 2023).
cervical cancer (3 papers, 2020 to 2023). A primary or metastatic malignant neoplasm involving the cervix. "We confirmed that ring finger protein 6 (RNF6) expression was significantly increased in cervical cancer (CC) tissues and HeLa cells, and this was associated with poor prognosis of CC patients." (PMID 34081837, 2021). "Ring finger protein 6 (RNF6) is implicated in various human malignancies, but its function in cervical cancer (CC) is incompletely understood." (PMID 34081837, 2021). "Last, RNF6 amplification was frequently observed in CRC, linked to cancer progression and metastasis as well as an increase in the phosphorylation levels of ERK1 in cervical cancer." (PMID 37751451, 2023). "The expression of NEDDL4, RNF6, MDM2 and TRIM11 is abnormal in cervical cancer." (PMID 32655987, 2020).
esophageal cancer (3 papers, 2023). A primary or metastatic malignant neoplasm involving the esophagus. "TCGA data analysis showed that RNF6 expression significantly increased in human esophageal cancer group compared with the paracancer control group (P<0.01)." (PMID 36845743, 2023). "Looking for esophageal carcinoma susceptibility in OMIM, we found listed at #133239 RNF6 and DCC; the latter, according to the STRING database, is linked by experiments/co-expression/co-occurrence to TRIO (5p15.2)(a) and MYO10 (5p15.1)(p)." (PMID 38248360, 2023). "RNF6 up-regulation promoted the progression of esophageal cancer and predicted poor prognosis." (PMID 36845743, 2023). "The results confirmed that RNF6 can promote the invasion and migration of esophageal cancer cells." (PMID 36845743, 2023). "RNF6/TGF-β1 promoted esophageal cancer progression through c-Myb." (PMID 36845743, 2023). "TCGA database was used to analyze RNF6 expression in normal tissues and esophageal cancer tissues." (PMID 36845743, 2023). "This study aimed to detect RNF6 expression in esophageal cancer." (PMID 36845743, 2023). "RNF6 exhibited a positive correlation with TGF-β and c-Myb and its co-expression in esophageal cancer." (PMID 36845743, 2023). "SiRNA interference vector and RNF6 overexpression plasmid were constructed, and RNF6 was transfected into Eca-109 and KYSE-150 esophageal cancer cell line." (PMID 36845743, 2023).
chronic myelogenous leukemia (2 papers, 2022 to 2024). "To confirm this hypothesis, we next examined the endogenous K48-linked polyubiquitination of RNF6 in both the MM cell line RPMI-8226 and chronic myelogenous leukemia CML cell line K562." (PMID 35926709, 2022).
lung carcinoma (2 papers, 2016 to 2023). "RNF6 is high in cisplatin-resistant lung cancer cell lines, indicating that it may also be closely related to drug resistance." (PMID 36845743, 2023).
Colon tumors (1 paper, 2021). "Colon tumors derived from RNF6 tg mice had reduced apoptosis compared to WT mice." (PMID 34611311, 2021). "Compared to WT group, colon tumors derived from Rnf6 tg mice exhibited higher Ki-67 and PCNA scores, consistent with the pro-tumorigenic effect of RNF6." (PMID 34611311, 2021).
dysplasia (1 paper, 2021). A usually neoplastic transformation of the cell, associated with altered architectural tissue patterns. "In addition, we found that wild-type mice from HGD group also expressed higher levels of RNF6 mRNA and protein compared to wild-type mice with no dysplasia in their colon tissues." (PMID 34611311, 2021).
gastric tumor (1 paper, 2022). "To investigate the effect of GLA on the mRNA stability of MDM2 and RNF6 in gastric tumor cells, we used actinomycin D, a transcription inhibitor widely used to inhibit the synthesis of new mRNA in the assessment of mRNA decay." (PMID 35814430, 2022).
melanoma (1 paper, 2021). A malignant, usually aggressive tumor composed of atypical, neoplastic melanocytes. "Besides RNF6, another RNF protein, RNF2, is also reported to possess dual roles in the regulation of oncogenic gene networks via transcriptional upregulation of Cyclin D2 in melanoma." (PMID 34611311, 2021).
myeloid leukaemia (1 paper, 2022). "Whereas in myeloid leukaemia, RNF6 promotes tumor growth by activating the PI3K/AKT/mTOR signaling pathway." (PMID 35369571, 2022).
myeloproliferative disorder (1 paper, 2017). A clonal hematopoietic stem cell disorder, characterized by proliferation in the bone marrow of one or more of the myeloid (i.e., granulocytic, erythroid, megakaryocytic, and mast cell) lineages. "The ring finger protein 6 (RNF6) is a ubiquitin ligase that was originally cloned in a genetic study of chromosomal rearrangements in myeloproliferative disorders." (PMID 28223545, 2017).
prostate tumor (1 paper, 2016). "Interestingly, RNF6 is also an AR corepressor, which demonstrated that it is a promoter-dependent coregulator of AR transcription in prostate tumor cells." (PMID 27365400, 2016). "We speculate that the discordant effects on AR-mediated transcription observed between the siRNA luciferase screen and reported AR coregulator functions of MDM2, RNF6, and USP10 in prostate tumor cells are due to differences in prostate tumor cell lines and reporter vectors." (PMID 27365400, 2016).
Sepsis (1 paper, 2022). Sepsis is defined as life-threatening organ dysfunction caused by a dysregulated host response to infection. "However, the functional role of RNF6 and its target protein in sepsis remains elusive so far." (PMID 36088389, 2022).
ZIKV infection (1 paper, 2026). "ZIKV infection in BMECs was significantly reduced following RNF6 knockout or knockdown but enhanced upon RNF6 overexpression or rescue." (PMID 41902231, 2026). "Evolutionary and structural analyses revealed that RNF6 is highly conserved between humans and tree shrews; molecular docking further identified shared NS5-binding residues (Gln-59, Arg-140), supporting the conserved proviral role of human RNF6 in ZIKV infection." (PMID 41902231, 2026).
cancer (15 papers, 2017 to 2024). A tumor composed of atypical neoplastic, often pleomorphic cells that invade other tissues. "Rnf6 is located on chromosome 13q12.13, and as a tumor promoter, RNF6 belongs to the E3 ligase family and is implicated in the growth, proliferation, adhesion, and invasion of cancer cells via the ubiquitination process." (PMID 35814430, 2022). "Furthermore, we found that anti-cancer drugs can trigger RNF6 with K48-linked auto-ubiquitination and proteasomal degradation." (PMID 35926709, 2022). "The zinc finger ubiquitin ligase RNF6 has been suggested as a possible focus for treatment in various cancer types." (PMID 39048945, 2024). "Based on the current findings, RNF6 seems to promote carcinogenesis by targeting different proteins in different cancers." (PMID 35369571, 2022). "The zinc finger ubiquitin ligase RNF6 has been proposed as a potential therapeutic target in several cancers, but understanding its molecular mechanism of degradation has been elusive." (PMID 35926709, 2022). "In prostate cancer, increased RNF6 expression promotes cancer development by enhancing the transcriptional activity of androgen receptor." (PMID 35369571, 2022). "RNF6 promotes drug resistance through JAK2/STAT3 signaling pathway and RNF6 upregulation can render cells resistant to multiple anti-cancer drugs." (PMID 35369571, 2022). "RING-finger protein 6 (RNF6) is an E3 ubiquitin ligase that is aberrantly upregulated in a range of cancers and plays important roles in cancer progression." (PMID 35369571, 2022). "Currently, accumulating studies have demonstrated that RING fingers (RNFs), such as RNF43, RNF20, RNF125, RNF6, and RNF183, are significantly associated with the development of cancers." (PMID 35568845, 2022). "RNF6 is an E3 ubiquitin ligase and increasing evidence has indicated that RNF6 is involved in the development of various cancers." (PMID 35369571, 2022). "RNF6 as a ubiquitin ligase has been reported in various cancers that modifies substrate proteins, therefore promoting their oncogenic activity." (PMID 35926709, 2022). "Although beyond the scope of our current study, it would be interesting to further investigate if RNF6 plays a role in the drug resistance of other types of cancers." (PMID 35369571, 2022). "As a RING-domain E3 ubiquitin ligase, several studies have demonstrated that RNF6 promotes tumorigenesis in multiple cancers via ubiquitination and degradation of target proteins." (PMID 34611311, 2021). "The RNF6 protein promoted ERα expression and stabilized the ERα/Bcl-xL axis, essential for cancer cells’ survival." (PMID 35822825, 2020). "For example, RNF6 mediates the polyubiquitination of androgen receptor and estrogen receptor thus increasing their activity and promotes cancer cell proliferation." (PMID 29997504, 2018). "We further revealed that RNF6 expression in both Y-79 and SO-Rb50 cells could render cells resistant to multiple anti-cancer drugs including carboplatin, vincristine and etoposide, an implication of RNF6 as a biomarker for RB drug resistance." (PMID 35369571, 2022). "Given the importance of RNF6 in RB drug resistance, it would also be valuable to check if RNF6 could be a therapeutic target for treating drug resistance in RB and/or other cancers." (PMID 35369571, 2022). "Given the E3 ubiquitin ligase property of both MDM2 and RNF6 in cancer metabolism, GLA might exert its antitumor effect on GC cells by blocking MDM2 and RNF6-mediated deregulated ubiquitination processes." (PMID 35814430, 2022). "RNF6 exerts different effects in various cancers and can be used as a tumor‐specific target." (PMID 34081837, 2021). "Our study confirmed that RNF6 may exert variable or even opposing roles in different tumor contexts and may be a novel candidate for cancer immunotherapy." (PMID 34081837, 2021). "The clinical trials have also confirmed the role of RNF6 in the malignancy of cancer cells." (PMID 32545648, 2020).
cancer (continued). "RNF6 is a member of the E3 ligase family and its role in cancer has been explored." (PMID 32545648, 2020). "RNF6 is involved in the essential pathways of cancer cell proliferation." (PMID 35822825, 2020). "So, recognizing the downstream targets of RNF6 is of importance in cancer therapy." (PMID 32545648, 2020). "Thanks to its function and involvement in many cancers’ pathogenesis, the RNF6 may be a molecular target in cancer therapy." (PMID 35822825, 2020). "In the present study, RNF6 is highly associated with ER and PR but not HER2, specifically RNF6 stabilizes ERα and upregulates the expression of Bcl-xL, a key gene in cancer cell survival." (PMID 28223545, 2017). "In addition, it seems that RNF6 functions distinctively in different cancers." (PMID 35369571, 2022). "Saponins have been reported to inhibit various signalling pathways, such as PI3K/AKT, AKT/MAPK, EGFR/PI3K/AKT, PI3K/AKT/mTOR, and RNF6/AKT/mTOR, which leads to its cytotoxic and apoptotic properties on various cancer cell lines." (PMID 39519799, 2024). "Additionally, RNF6 is silenced, which increases GSK3 activity, decreases p-GSK3 inhibition of the Wnt/β-Catenin pathway in cancer cells, and suppresses MAPK/ERK signaling, which in turn reduces cell growth and proliferation." (PMID 37628788, 2023). "RNF6 can regulate the activation of the Wnt/β-catenin pathway and JAK/STAT3 pathways in cancer." (PMID 35814430, 2022). "RNF6, a RING-type E3 ubiquitin ligase, has been found to play an oncogenic role in cancer." (PMID 35814430, 2022). "Therefore, our results reveal that RNF6 is a RING E3 ligase that undergoes auto-ubiquitination, which could be abolished by USP7 and induced by anti-cancer drugs." (PMID 35926709, 2022).
tumor (14 papers, 2017 to 2024). "The functions of RNF6 co-expressed genes were correlated with tumor proliferation, invasion and metastasis, and EMT." (PMID 36845743, 2023). "Transwell invasion assay revealed that the number of tumor cells below the Transwell compartment membrane significantly increased in the overexpressed RNF6 group, and the invasion ability of cells was significantly enhanced (P<0.01)." (PMID 36845743, 2023). "Taken together, these data suggest that tumor promoting function of RNF6 in CRC was dependent on the upregulation of SF3B2 expression." (PMID 34611311, 2021). "In vitro experiments suggested that RNF6 inhibited apoptosis to promote cell proliferation, which was consistent with the results obtained from tumor tissues." (PMID 34081837, 2021). "As an upstream component of the ubiquitin–proteasome system, E3 ligase RNF6 has attracted increasing attention in the tumor field." (PMID 34081837, 2021). "Next, we collected 20 pairs of adjacent normal tissues and tumor tissues from CC patients to measure the protein level of RNF6 that was also overexpressed in tumor tissues." (PMID 34081837, 2021). "Patients with cisplatin‐resistant lung adenocarcinoma have increased expression of RNF6 in tumor cells." (PMID 34081837, 2021). "Meanwhile, IHC staining of mouse and human tumor tissues also showed the same result of RNF6 location." (PMID 34611311, 2021). "SF3B2 knockout abrogated the tumor promoting effect of RNF6 overexpression, whereas the reexpression of SF3B2 recused cell growth and migration/invasion in RNF6 knockout cells, indicating that SF3B2 is a functional downstream target of RNF6 in CRC." (PMID 34611311, 2021). "The RNF6 protein stabilized the glucocorticoid receptor, leading to the activation of anti-apoptotic proteins Bcl-xL and Mcl-1, followed by tumor proliferation." (PMID 35822825, 2020). "Studies in tumor cells and model organisms using inhibitors such as total saponins from Paris forrestii (TSPf), ellagic acid, or microRNA molecules show the effectiveness of inhibiting RNF6, and through it, the pathways of tumor cell proliferation." (PMID 35822825, 2020). "Consistent with the findings in cultured cell lines, TSPf also downregulated RNF6 expression along with inactivated AKT/mTOR signaling in tumor tissues." (PMID 29997504, 2018). "Furthermore, the expression of MDM2 and RNF6 was increased in the tumor tissues in H. pylori and MNU group, and the effect was abrogated by GLA treatment." (PMID 35814430, 2022). "However, little is known with regards to the potential role of RNF6-mediated transcriptional regulation in tumor development and progression." (PMID 34611311, 2021). "Moreover, RNF6 tg mice showed a significant increase in both tumor multiplicity (1.5 vs 0.3; P = 0.003) and burden (2.4 vs 0.8 mm; P = 0.004) compared to wild-type mice." (PMID 34611311, 2021). "Moreover, the combination of 5-fluorouracil (5-FU) plus pladienolide B exerted synergistic effects in CRC with high RNF6 expression, leading to tumor regression in xenograft models." (PMID 34611311, 2021). "Consistent with the tumor tissues, RNF6 expression was high in the CC cell line." (PMID 34081837, 2021). "The RNF6 was knocked down by shRNA, and the tumor growth was inhibited." (PMID 35822825, 2020). "There are also reports that the RNF6 can be considered a prognostic factor in some neoplasms." (PMID 35822825, 2020). "Results showed that after RNF6 inhibition, the scratch area of Eca-109 and KYSE-150 cells was small, their migration ability decreased (P<0.05), and the number of tumor cells below the Transwell compartment membrane significantly decreased (P<0.05)." (PMID 36845743, 2023). "Among the genes negatively regulated by KDM4B, STARD7, CPA4, FKBP14, and RNF6 have been shown to regulate cell proliferation and/or metastasis, whereas DYRK2 is a known tumor suppressor." (PMID 34766154, 2021).